CD80 (CD80 molecule)
Diseases named in the same sentence as CD80 in open-access papers (continued):
Sharing a sentence is not in itself a finding about the gene and the disease.
viral infection (38 papers, 2009 to 2025). "External factors like viral infections and Treg function can impact the expression of B7-1 (CD80) on podocytes, potentially causing podocyte cytoskeletal disarray and severe proteinuria." (PMID 38288116, 2023). "Recently, CD80 expression on memory CD8+ T-cells after acute viral infections has been reported to play an important role in suppressing excessive CD8+ T-cell recall responses, leading to an appropriate recall immune response." (PMID 34635773, 2021). "Having correlated gene-specific viral integration with elevated PD-L1 and PD-L2 expression in HPV-positive HNSC, we next correlated any viral infection with PD-L1, PD-L2, PD-1, CD80, CD86, CTLA-4, Tim-3, LAG3, and 4-1BB expressions." (PMID 30911684, 2019). "Since viral infections trigger interferon-induced gene expression in epithelial cells to orchestrate immune responses, we also stained for co-stimulatory molecules CD80 and CD86, or immune-activating molecules CEACAM5 and CEACAM6." (PMID 36827975, 2023). "Higher expression of the suppressive marker PD-L1 and low expression of maturation markers CD86 and CD80 might be a result of viral infection." (PMID 33003471, 2020). "Given the fundamental functions of activated microglia during viral infection of the brain, we aimed to assess the expression of microglial activation markers CD86 and CD80 on microglia infected with either MP-12 or ZH501." (PMID 38392897, 2024). "The B7 family proteins B7.1 (CD80) and B7.2 (CD86) are two well-studied costimulatory ligands that play critical roles in host T cell immunity against viral infection." (PMID 37626059, 2023). "By contrast, CTLA4 is another ligand for CD80/CD86 which presents even a higher avidity than CD28, acting as a critical inhibitor of T-cell activation and proliferation in several viral infections." (PMID 36713151, 2022). "This aligns with the fact that during viral infections, the secretion of IL-10 has been found to inhibit the expression of major histocompatibility class II (MHC II) and co-stimulatory molecules CD80 and CD86 on APCs." (PMID 35572964, 2022). "During viral infections, neutrophils express HLA-DR (MHC class II), CD80, and CD40, which contribute to antigen-specific CD4+ T-cell response." (PMID 34411088, 2021). "As matched, uninfected BMDC cultures from each individual bat are used to calculate fold change in gene expression for each timepoint, the increase in CD80 and CCL3 transcription coincided only with viral infection." (PMID 31681302, 2019). "The surface cell stimulator ligands CD80 and CD86 play a vital part in the maintenance and initiation of the immune response against viral infections." (PMID 28265274, 2017). "With regard to CD80 expression, M0 and M(LPS + IFN-γ) cells increased surface levels following viral infection, while M(IL-4) cells expression of CD80 remained largely unchanged (column 1)." (PMID 29250063, 2017). "In cells sorted three days after viral infection with Theiler's murine encephalomyelitis virus, surface receptors (including CD45, CD11b, CD40, CD80, CD86) were upregulated in spinal microglia compared to brain microglia." (PMID 24914808, 2014). "The viral infection inhibited the expression of cell maturation surface markers (CD40, CD80 and CD83) and MHCI, and impaired the ability of P3-infected DCs for activating allogeneic naïve T cells." (PMID 21269456, 2011). "Moreover, in general, following viral infection, T-cell co-signaling pathways are typically activated, involving interactions between CD28 on T cells and B7-family ligands, such as CD80 and CD86, on DCs." (PMID 40333058, 2025). "Although both CD80 and CD86 provide costimulatory signals through CD28, it remains unclear whether they can fully compensate for each other’s functions during viral infections." (PMID 41280933, 2025).
viral infection (continued). "While previous studies suggest the overlapping function of CD80 and CD86 in antibody responses, during virus infection CD86 expression on B cells but not CD80 is critical for Tfh cell generation and function." (PMID 30158933, 2018). "Cluster 5 is related to immune tolerance to viral infections, and its subclusters 5–14 are related to TIGIT and CD155, which are considered to be the third molecules for immune checkpoints following PD-1/PDL-1 and CTLA4/CD80/86, whose inhibitors have already been used in pharmaceuticals." (PMID 34811710, 2022). "At the chronic viral infection phase, KC showed no increased transcription of activation markers Cd80 and Cd86, but an increased expression of genes related to antigen presentation, whereas monocytes were more activated and expressed higher levels of Tnf transcripts." (PMID 27812182, 2016). "Likewise, C. butyricum-colonized mice retained a low level of either MHC-I- or CD80-upregulated PBMC and spleen mononuclear phagocytes compared to Abx-treated mice following viral infection at 3 dpi." (PMID 33975932, 2021). "Importantly, since we used comparisons with cells infected with mut or empty vector in these assays, our approach ruled out the possibility that changes in MHC II, CD80 and CD86 were related to viral infection." (PMID 23251709, 2012).
diabetes (36 papers, 2006 to 2025). "Diabetes promoted macrophage infiltration into the inner retina, as evidenced by increased CD80 colocalization with F4/80 in retinal sections." (PMID 37392853, 2023). "As expected, mice treated with anti-CD80/86 Ab alone showed a delay in diabetes development but rapidly developed disease upon treatment cessation; analysis of blood samples confirmed a loss of Treg in these mice." (PMID 36347877, 2022). "We also analyzed the mean fluorescence intensity (MFI) of these molecules and found that diabetes enhanced the MFI of CD80 and CD86 on B cells in EAMG rats." (PMID 34702288, 2021). "First, spontaneous diabetes incidence is increased to 100% and disease onset is accelerated in NOD mice deficient in either CD28 or CD80 and CD86 that is directly correlated with a quantitative decrease in Tregs by >80%." (PMID 31281853, 2019). "In addition, when CD80 was expressed on pancreatic β cells from B6 mice backcrossed once with genetically susceptible NOD, the onset rate of diabetes and the severity of the autoimmune response also increased." (PMID 39777226, 2024). "Aberrant expression of CD80 in pancreatic islets causes β-cell destruction in low-dose streptozotocin-induced diabetes, because the ectopic expression of CD80 may activate T cells via CD282." (PMID 36180526, 2022). "Diabetes promoted B cell activation and upregulated the expression of CD80 and CD86, which may account for the differentiation of CD4+ T cells from Treg cells towards Th1/Th17 cells." (PMID 34702288, 2021). "Under additive genetic models, CD28-rs3116494 (OR = 1.29 [95% CI 1.11, 1.51], P = 0.0011) and CD80-rs3850890 (OR = 1.16 [95% CI 1.02, 1.31], P = 0.0283) were associated with DKD susceptibility adjusted for age, gender, body mass index (BMI), duration of diabetes, and HbA1c." (PMID 33958973, 2021). "When CD80 was co-expressed with TNF-α or IL-2, a large proportion of mice developed severe pancreatitis and diabetes mellitus." (PMID 39777226, 2024). "The expression levels of HLA-DR, CD80, and CD86 were low while those of of PD-L1 were high in uninfected MDMs derived from patients with diabetes; as a result of Mtb infection, changes were only observed in the expression levels of PD-L1." (PMID 29513874, 2018). "Previous experiments with adoptive transfers of mature bone-marrow derived DCs expressing high levels of co-stimulatory molecules, such as CD80, CD86 and CD40, significantly reduced diabetes incidence in NOD mice." (PMID 25166904, 2014). "On the other hand, the development of diabetes in NOD mice, a model for insulin-dependent diabetes mellitus (IDDM), is exacerbated by treatment with anti-CD80 mAb and is blocked by treatment with anti-CD86 mAb." (PMID 22997525, 2012). "In diabetic mice and in lupus-prone MRL/lpr mice, the blockade of CD80 worsens the severity of both diseases, whereas blockade of CD86 prevents diabetes and has mild effects on lupus." (PMID 16507174, 2006). "Diabetes incidence in the anti-CD80/86 Ab plus IL-2c group, but not other treatment groups, was significantly different from the control group." (PMID 36347877, 2022). "CD80 is not exclusive to lymphocytes, as podocytes in primary focal and segmental glomerulosclerosis and diabetes and podocytes and tubular cells in IgA nephropathy express CD80 in human biopsies." (PMID 27733175, 2016). "As the basal expression of molecules important in macrophage activation has not been previously reported in patients with diabetes, we evaluated the expression of HLA-DR, CD80, CD86, and PD-L1 in MDMs derived from patients with diabetes compared to that in MDMs derived from healthy subjects." (PMID 29513874, 2018). "Unloaded tolDCs treated with antisense oligonucleotides against costimulatory molecules (CD40, CD80, and CD86) delayed diabetes in NOD mice, but not if pulsed in vitro with cell lysate from the NIT-1 β-cell line." (PMID 31139178, 2019).
COVID-19 (30 papers, 2021 to 2025). A disease caused by infection with severe acute respiratory syndrome coronavirus 2. "Here we provide additional evidence supporting the utility of blocking the CD80/86 axis to prevent COVID-19 associated hyperinflammation." (PMID 34075090, 2021). "Regarding DC functionality, it was shown that the expression level of the costimulatory and maturation-associated markers CD86 and CD80 was significantly lower, while that of the suppressive molecule PD-L1 was enhanced in COVID-19 patients with respect to healthy individuals." (PMID 34209845, 2021). "In COVID-19 patients, abnormal activation of macrophages expressing M1/M2 polarization markers (CD68, CD80, CD163, and CD206) in the lung is associated with the production of cytokines, including IL-6, IL-10, and TNF-α, as indicated by previous studies." (PMID 39100091, 2024). "In a cohort of patients recovering from severe COVID-19, increased markers indicating immune system activation were noted, particularly in antigen-presenting cells co-expressing CD80." (PMID 38468605, 2024). "Overall, PCA of classical monocytes revealed an acute-phase COVID-19 clustering pattern upon bacterial challenge, which was strongly associated with low expression of HLA-DR, CD86, CD80 and a high expression of CD163, CX3CR1 and CD11b." (PMID 35007290, 2022). "TYMS is involved in the CD80/86 proinflammatory axis, and is upregulated in severe COVID-19 patients." (PMID 35746678, 2022). "In support of the safety and utility of CD80/86 axis blocking to prevent severe COVID-19, there is substantial epidemiological evidence showing that abatacept does not increase the risk of serious infections." (PMID 34075090, 2021). "In particular, pDC from asymptomatic COVID-19 patients mainly expressed PD-L1, while cells derived from severe COVID-19 patients were consistently represented by the PD-L1+CD80+ phenotype." (PMID 34209845, 2021). "Here we provide exploratory evidence that abatacept, a drug that blocks CD80/86 co-stimulation, produces changes at the systemic level that are highly antagonistic of the proinflammatory processes elicited by COVID-19." (PMID 34075090, 2021). "Our results suggest that T cell stimulation by CD80/86-expressing macrophages is a driver of COVID-19 severity." (PMID 34075090, 2021). "Analysis of previous single-cell RNA-seq data from bronchoalveolar lavage fluid from mild and severe COVID-19 patients and controls, reinforce the implication of the CD80/86 proinflammatory axis." (PMID 34075090, 2021). "Finally, immunohistochemistry validated the accumulation of both CD163+ macrophages and CD80+ proinflammatory macrophages in pancreatic tissues of COVID-19 patients." (PMID 39232561, 2024). "In support of this hypothesis, a recent study found that COVID-19 patients had reduced upregulation of CD80 on monocytes and abrogated release of IL-6, TNF, IL-1a and IL-1b in response to Candida albicans." (PMID 38169876, 2023). "Moreover, while CD80 was significantly upregulated in healthy, mild and moderate COVID-19 monocytes after SARS-CoV-2 stimulation, only healthy monocytes increased the expression of CD86 after stimulation." (PMID 36572683, 2022). "Moreover, dendritic cells, obtained from patients with COVID-19, expressed significantly less CD80, CD86, CCR7, and HLA-DR in response to in vitro stimulation compared to those from HDs." (PMID 36012146, 2022). "Our results provide additional evidence at the functional level that blocking the CD80/86 axis could be a useful therapeutic approach to prevent severe COVID-19." (PMID 34075090, 2021). "The results of our study provide additional functional evidence that blocking of the CD80/86 axis could prevent reaching the hyperinflammatory stage observed in severe COVID-19." (PMID 34075090, 2021).
COVID-19 (continued). "Based on previous epidemiological evidence from rheumatic patients treated with several targeted immunomodulators, we hypothesized that blocking of the CD80/86 proinflammatory axis could be a useful therapeutic approach to prevent severe COVID-19." (PMID 34075090, 2021). "Due to the attenuated immune response of COVID-19 patients, particularly the reduced upregulation of monocyte CD80 expression and the suppressed release of key cytokines such as IL-6, TNF, IL-1a, and IL-1b, this may lead to a decreased ability to clear C. albicans in these patients." (PMID 38658823, 2024). "Based on recent epidemiological evidence, we hypothesized that CD80/86 signaling is essential for this hyperinflammation, and that blocking this proinflammatory axis could be an effective therapeutic approach to protect against severe COVID-19." (PMID 34075090, 2021). "The response to agonist stimulation was also greatly limited in pDCs from severe COVID-19 patients compared to healthy donors and patients with mild symptoms/asymptomatic, notably as shown by the level of activation markers (CD83, CD80, and PD-L1; red arrows)." (PMID 36755036, 2023). "Although they were not enriched in autoreactive B cells, two distinct memory populations (CD80+/ISG15+ and CD11c+/SOX5+/T-bet+/−) with signs of autoreactivity were identified, which were considered to be the source of COVID-19 autoantibodies." (PMID 37243231, 2023). "Conversely, hospitalized COVID-19 patients > 70 years of age showed increased blood plasmablast B cells (CD19low, CD20-, IgD-, IgM-, CD80+, CD38+), compared to hospitalized COVID-19 patients < 60 years of age." (PMID 36941580, 2023). "Upon bacterial challenge, classical monocytes from COVID-19 patients (acute- and rec-phase) displayed high expression of CD163 and CD11b, but low expression of the activation markers HLA-DR, CD86 and CD80." (PMID 35007290, 2022). "The R848-treated myeloid populations from COVID-19 patients also showed reduced expression of HLA-DR and enhanced expression of CD38, CD68, CD80, and CD206, which was similar to the untreated condition." (PMID 36085197, 2022). "In lung, CD40, CD80, CD83 and HLA-DQA2 were upregulated while CD86 and FCER1A were decreased in mild COVID-19 as compared to healthy controls." (PMID 34502134, 2021). "The dysregulation of DC function in COVID-19 was also presented by the expression of the maturation marker (CD83), T-cell stimulation molecules (CD40, CD80, CD86) and antigen presentation molecules (HLA-DQA2 and FCER1A)." (PMID 34502134, 2021). "At the same time, we also detected the expression of CD80 on DCs, and found that CD80 showed a significant increase on pDCs of pregnant and non-pregnant patients infected with COVID-19." (PMID 39113896, 2024). "Therefore, the level of CD80+- and CD86+-B cells in recovered COVID-19 should be studied to determine if those cells have a role in protecting the individuals from reinfection." (PMID 35069575, 2021). "Reduced inflammatory cytokine expression was also linked with a downregulation in the expression of phenotypic markers, including CD80 and CD206, which were recently found to be upregulated on monocytes from patients with COVID-19 who express higher levels of proinflammatory cytokines." (PMID 34238021, 2021). "Our analysis showed a significantly higher intensity of CD80 expression on monocytes in COVID-19 patients compared to HCs without significant difference between patients with mild/moderate and those with severe disease." (PMID 33947753, 2021). "Amongst T-cell and monocytes/macrophages, some immune-stimulatory or auto-regulatory interactions were seen (CTLA4 or CD28/CD80 or CD86, CCL5/CCR5), but specific epithelial to T-cell interactions in critical COVID-19 were limited to pro-inflammatory ICAM1-mediated interactions." (PMID 33473155, 2021).
COVID-19 (continued). "Although expanded PBs were clearly linked to plasma autoantibodies in our patients, we found evidence that not the PBs themselves, but atypical B cells with low T-bet expression as well as CD80+/ISG15+ memory B cells harbor immunogenetic and transcriptional signs of autoreactivity in COVID-19." (PMID 34723157, 2021). "To explore whether the monocytes from COVID-19 patients exhibit a similar phenotype, we evaluated the expression levels of several activation markers, including CD33, CD86, CD80, HLA-DR, and CD40, in monocytes isolated from the peripheral blood mononuclear cells (PBMCs) of HD, MP and SP group." (PMID 39996729, 2025). "However, when this study was conducted, blocking of the proinflammatory CD80/86 axis with abatacept had not been yet considered as a candidate therapeutic approach to prevent severe COVID-19." (PMID 34075090, 2021). "In sharp contrast, pDCs from severe COVID-19 patients failed to be activated by SARS-CoV-2-infected cells, as demonstrated by the absence or low detection of IFN-α, IFN-λ, CD83, and CD80/PD-L1 as compared to healthy donors and mild/asymptomatic patients (red bars and arrows)." (PMID 36755036, 2023).